BCL2 (BCL2 apoptosis regulator)
Diseases named in the same sentence as BCL2 in open-access papers (continued):
Sharing a sentence is not in itself a finding about the gene and the disease.
cancer (continued). "The most prominent example of this is the overexpression of pro-survival BCL-2 proteins, a common feature in diverse cancers." (PMID 27455839, 2016). "Targeting BCL-2 anti-apoptotic complexes and pathways in cancer is a productive drug discovery and development field." (PMID 27520705, 2016). "Bufalin can trigger mitochondria-mediated apoptosis in many cancer cells through downregulation of Bcl-2/Bcl-xL and/or upregulation of Bax/Bad/Bid." (PMID 26770191, 2015). "Evidence suggests that the Bcl-2 antagonist of cell death (BAD)-mediated apoptotic pathway influences cancer chemoresistance." (PMID 25653146, 2015). "Bcl-2 overexpression confers cancer cell resistance pertaining to taxanes and, since KEMTUB10 does not prominently rely on Blc-2 phosphorylation to induce apoptosis, the compound is less susceptible to acquired Bcl-2 resistance." (PMID 26563258, 2015). "Several studies have demonstrated that overexpression of the pro-survival protein Bcl-2 confers resistance to apoptosis by apoptotic inducers in several cancers, including breast." (PMID 25848915, 2015). "Since then more than 25 pro- and anti-apoptotic Bcl-2 proteins have been detected and characterized in regard to their clinical relevance in a repertory of different cancers." (PMID 25885284, 2015). "BCL2 has been considered an attractive target for anticancer therapies as it can be pharmacologically inhibited and, thus, potentiate apoptosis in cancer cells." (PMID 25762636, 2015). "Keap1 appears, through controlling Bcl-2 expression levels, to function as a molecular sensor to regulate apoptosis in cancer cells harboring oncogenic ras." (PMID 26041886, 2015). "The JAK3-STAT5a pathway is responsible for maintaining levels of the anti-apoptotic protein BCL-2 in T cells and its impairment during cancer leads to decreased BCL-2 levels." (PMID 26464579, 2015). "A-1210477 synergized with the Bcl-2/Bcl-xL inhibitor Navitoclax to kill a variety of cancer cell lines." (PMID 26405162, 2015). "NR4A1 is a nuclear receptor; however, treatment of some cancer cell lines with apoptosis-inducing agents results in the induction and nuclear export of NR4A1 which associates with mitochondrial bcl-2 to form a pro-apoptotic complex." (PMID 26035713, 2015). "In our study, following treatment of the cancer cells with the compound Radix Sophorae Flavescentis injection, Bcl-2 expression markedly decreased and Bax expression significantly increased, indicating an increase in apoptosis." (PMID 26622820, 2015). "Overexpression of Bcl-2 is frequently observed in several types of cancer such as breast, lung, ovarian, melanoma cancers, and is often associated with unfavorable outcome." (PMID 26535028, 2015). "Bortezomib inhibits the ubiquitin/proteasome pathway to achieve its anti-cancer effect and its well characterized activity is the NF-κB inhibition through which the anti-apoptotic bcl-2 expression is down-regulated and apoptosis is subsequently induced." (PMID 26472030, 2015). "It has been found that Bcl2 play an important role in resistance of cancer cells to chemotherapy or radiation therapy." (PMID 26074734, 2015). "c-Myc, Bcl-2 and survivin are well known cancer promoter genes and their transcription can be triggered by STAT3, Notch and Wnt signaling, respectively." (PMID 25896424, 2015). "Bcl-2 is currently considered to be an important factor for the generation, metastasis and angiogenesis of malignant tumours." (PMID 25667663, 2015). "PI3K/Akt signaling pathway promotes cancer cell survival by modulating Bcl-2 members and drug-resistance proteins." (PMID 26359357, 2015). "Interplay among pro-apoptotic (Bax, Bad) and anti-apoptotic (Bcl–2, Bcl-xl) proteins influences the sensitivity of cancer cells to drug-induced apoptosis." (PMID 26436418, 2015). "Technically, it is quite challenging to pin-point the origin of these Bcl-2 positive CECs in cancer patients." (PMID 26509633, 2015).
cancer (continued). "BCL2 is a critical anti-apoptotic protein involved in resistance to DNA damaging agents in many cancer types, for which pharmacological inhibitors are available, some of which have shown promising results in the treatment of solid tumors." (PMID 25762636, 2015). "Previous studies have noted that melatonin alters the balance between BAX and BCL-2 in some cancer cells by up-regulating BAX expression, resulting in MOMP and cytochrome c release." (PMID 26025920, 2015). "The expression levels of Bcl-2 have been demonstrated to be a crucial factor in cancer progression and development." (PMID 26041886, 2015). "Evasion of apoptosis is a feature of many cancer cells that is involved in overexpression of Bcl2, which inhibits cell apoptosis and enhances chemoresistance." (PMID 26556865, 2015). "Antiapoptotic proteins such as Bcl-2 and XIAP prevent loss of MMP and expression of caspase-3 activation leading to inhibition of apoptosis during cancer treatment." (PMID 26539482, 2015). "Overexpression of the BCL-2 is frequently detected in many types of human cancers and promotes resistance to chemotherapy." (PMID 26199906, 2015). "We report for the first time that a BH3 mimetic, Sabutoclax, which functions as an inhibitor of all anti-apoptotic Bcl-2 proteins, induced cancer-specific cell death in an Mcl-1-dependent manner through both apoptosis and toxic mitophagy." (PMID 26009874, 2015). "Similar to a small-molecule Bcl-2 antagonist with duel pro-apoptotic functions in resistant cancer cells, the current study indicates that VTD can exhibit subcellular targeting effects that encompass two independent apoptotic pathways." (PMID 26188124, 2015). "Navitoclax (ABT-263) is a first-in-class Bcl-2 and Bcl-xL antagonist that restores the ability of cancer cells to undergo apoptosis." (PMID 25685063, 2015). "In summary, we have demonstrated that Bcl-2 ubiquitination and degradation play an important role in sensitizing cancer or transformed cells expressing oncogenic ras to apoptosis triggered by PKC inhibition." (PMID 26041886, 2015). "In other cancers types, we also observed a change in the Bcl-2/Bax ratio with increase in cytochrome C and caspase 9 levels with PC treatment." (PMID 26499490, 2015). "The sensitivity of cancer cells to an apoptotic stimulus is dependent on the ratio of Bax/Bcl-2 or Bcl-xL at the mitochondrial levels." (PMID 26093086, 2015). "As predicted, A-1210477 synergizes with the BCL-2/BCL-XL inhibitor navitoclax to kill a variety of cancer cell lines." (PMID 25590800, 2015). "For example, overexpression of anti-apoptotic BCL-2 proteins confers a favorable prognosis in certain cancer types whereas genetic deletion of the pro-apoptotic BH3-only proteins BID and PUMA inhibits tumorigenesis in some settings." (PMID 25702873, 2015). "When Bim is expressed at relative high basal levels, the cancer cells have often developed a mechanism (e.g., concomitant Mcl-1 or Bcl-2 upregulation) that antagonizes the pro-apoptotic function of Bim." (PMID 26405162, 2015). "Apoptotic cell death in the PRE, EA-fraction and EC+GA+UA treated cancer cell cultures was significantly greater than in normal cells due to suppression of anti-apoptotic protein Bcl2 following treatment." (PMID 26284809, 2015). "One of the target genes, Bcl-2, is an oncogene which acts to suppress cellular apoptosis; therefore, overexpression of Bcl-2 inhibits apoptosis in damaged cells, leading to uncontrolled cellular proliferation that drives the development of cancer." (PMID 25874209, 2015). "Bcl-2 is an important player in multidrug resistance in different types of cancer and miR-15a/16 were shown to induce apoptosis by targeting Bcl-2 in CLL." (PMID 26397135, 2015). "BDA-366 not only induces apoptosis but also autophagic cell death of cancer cells by disruption of Bcl2 activity." (PMID 26682258, 2015).
cancer (continued). "ABT-263 simultaneously inhibits Bcl-2, Bcl-xL, and Bcl-w; two of which (Bcl-2 and Bcl-xL) are co-expressed in many human cancer cells." (PMID 26188358, 2015). "Our study suggested that Bcl-2 is an attractive target for sensitizing cancer cells expressing oncogenic K-ras after being treated with the PKC inhibitor." (PMID 26041886, 2015). "Navitoclax (ABT-263) is a Bcl-2/Bcl-xL inhibitor that restores the ability of cancer cells to undergo apoptosis." (PMID 25685063, 2015). "It has been previously reported that downregulation of BCL2 by antisense oligonucleotides or siRNAs leads to apoptosis, and sensitizes cancer cells to chemotherapy and radiation therapy." (PMID 26394044, 2015). "Extended mitotic arrest following treatment of cancer cells with microtubule-targeting agents led to phosphorylation of Bcl-2 and Bcl-x followed by Noxa-dependent Mcl-1 degradation." (PMID 26405162, 2015). "The cooperative regulation of the BCL2 and NOXA genes by SATB1 at higher-order chromatin structure levels is significant in view of the profound association of SATB1 with cancer development and chemotherapy resistance." (PMID 26422397, 2015). "The small hairpin RNA (shRNA)-expressing plasmid DNA targeting the Bcl-2 gene (shBcl-2) as a model gene was encapsulated in nanoparticles (NPs) to treat cancer more efficiently." (PMID 25852425, 2015). "TTP negatively regulates cell growth in several cancer cell types by inhibiting the stability of many mRNA implicated in cell cycle (c-Myc, cyclin D1), inflammation (TNFα, COX-2), apoptosis (Bcl-2, Mcl-1), and angiogenesis (VEGF)." (PMID 26343742, 2015). "It has been postulated that rapidly growing cancer cells tend to activate the Bak/Bax pro-apoptotic signaling pathway, the activation of which is counteracted by increased levels of pro-survival Bcl-2 members." (PMID 26447615, 2015). "ABT-737 is a small-molecule inhibitor of Bcl-2, Bcl-xL and Bcl-w that has been investigated in several human cancers, including hematological neoplasias." (PMID 26392332, 2015). "Our study suggested that PKC cooperates with oncogenic K-Ras to promote or support the survival of cancer cells, probably via increasing Bcl-2 stability." (PMID 26041886, 2015). "Validating this, the activation level of STAT3, as marked by p-Tyr705, particularly in the mitochondria, was significantly higher in Bcl-2-overexpressing cancer cells." (PMID 26430964, 2015). "All these genes have already been associated with hypermutated regions in BCLs (BCL2, BCL6, BCL7A, BIRC3, CIITA and ST6GAL1) or listed in the Cancer Gene Census (BCL2, BCL6, BCL7A, BIRC3, CIITA, IGLL5 – in the IGL@ locus – and LPP)." (PMID 25903198, 2015). "The favorable prognosis previously observed in Bcl-2-positive cancer seems to reflect the indirect effect of frequently coexpressed hormone receptors and adjuvant endocrine therapy." (PMID 26472348, 2015). "Due to the fact that it is overexpressed in numerous cancer types, including female cancers, finding phytochemicals which target Bcl-2 is advantageous." (PMID 26075205, 2015). "The BH3 mimetic Sabutoclax, which significantly targets Mcl-1 in addition to the other anti-apoptotic Bcl-2 proteins, induced cancer-specific cell death in OSCC alone or in combination with Celecoxib." (PMID 26009874, 2015). "Taken together, these data are consistent with the notion that loss of KEAP1 affects multiple targets that are relevant to cancer cell biology, including not only NRF2, but also IKKβ and BCL2." (PMID 26301506, 2015).
cancer (continued). "In response to growth-related stimulation, Bcl-2 was shown to be upregulated and further desensitize cancer cells to apoptosis." (PMID 26041886, 2015). "H2O2 can specifically oxidize and activate the intrinsic apoptosis pathway (i.e., reduce the mitochondrial membrane potential, inhibit expression of Bcl-2, and activate caspase-8 and caspase-3, and therefore inducing apoptosis in cancer cells." (PMID 26330167, 2015). "Apoptosis is attenuated in cancer cells because of the abundance of antiapoptotic BCL-2 proteins and/or prevention of apoptosis induction." (PMID 26136077, 2015). "Nearly all of the impacts of Bcl–2, Bcl-xl on cancer were attributable to their effects on the apoptotic pathway." (PMID 26436418, 2015). "To functionally characterize the effects of our identified alcohol-regulated miRNAs, we investigated their influence on cellular proliferation as well as their relationship with established cancer genes, including the anti-apoptotic gene BCL-2." (PMID 26472042, 2015). "And this in fact has formed the basis for developing peptide or small molecule mimetics of these “sensitizing” BH3-only proteins, as a way to therapeutically adjust the Bcl-2 rheostat to favor cell death instead of cell survival in the cancer setting." (PMID 26231047, 2015). "The Bax expressions of 100 and 200 μg/mL UDCA treated cancer cells were also higher than control cells, and Bcl-2, Bcl-xL expressions were lower than those of control cells." (PMID 25951128, 2015). "Evasion of apoptosis is a feature of many cancer cells that is involved in overexpression of Bcl2 (B-cell lymphoma 2)." (PMID 26556865, 2015). "Bcl-2 and Cyclin D1 proteins (P < 0.05) was observed in the majority of cancer cases as compared to those in precancer and adjacent normal controls." (PMID 26581505, 2015). "In many cancers the equilibrium between pro- and antiapoptotic BCL-2 proteins is perturbed (e.g. by overexpression of antiapoptotic BCL-2), resulting in evasion of apoptosis." (PMID 25781619, 2015). "Concomitantly, the extract also decreased pro-survival factors, GSH and Bcl-2 in the cancer cells, providing additional evidence that the mango kernel extract has anticancer properties." (PMID 25881293, 2015). "Previous reports showed that high Bcl-2 or low Mcl-1 expression correlate with in vitro sensitivity of several cancer cell lines to ABT-737." (PMID 26392332, 2015). "Previous studies showed that PTL targeted NF-kB, Stat3, Bcl-2, reactive oxidative species (ROS) in cancer cells." (PMID 25658946, 2015). "Studying the expression of bcl-2 in cancer cells the investigation has showed that 40 % of tumors were bcl-2 positive." (PMID 26112049, 2015). "With the gradual increase in the drug concentration, the mRNA expression levels of caspase-3, Bcl-2 and Bax in the cancer cells were altered in a dose-dependent manner." (PMID 26622820, 2015). "At the concentration of 400 μg/mL, UDCA treated cancer cells showed the highest Bax expression, and lowest Bcl-2, Bcl-xL expressions." (PMID 25951128, 2015). "This knowledge is essential in order to develop further new therapeutic approaches for cancer treatment, in which mRNA destabilization can be promoted by targeting specific RBPs to decrease the expression of oncogenes, like Bcl2." (PMID 25680182, 2015). "The link of Ca2+ to cancer and apoptosis was initially accepted with the discovery that the classical antiapoptotic protein Bcl-2 affected Ca2+ signaling." (PMID 25544762, 2015). "Before testing the combination effect of TRAIL and the Bcl-2 family inhibitors, we examined the expression of anti-apoptotic Bcl-2 family proteins (Bcl-2, Bcl-xL, and Mcl-1) in nine cancer cell lines." (PMID 26506422, 2015).
cancer (continued). "The discovery of BCL-2 established a new paradigm in cancer biology, namely that apoptosis defects give cells selective survival superiority." (PMID 26132559, 2015). "This indicates a critical difference between normal versus cancer cells on the one hand and between different subsets of cancer cells on the other hand in their addiction to Bcl-2 at level of their ER/IP Rs." (PMID 25897426, 2015). "Targeting Bcl-2 in combination with inhibitors of autophagy in chemoresistant cancer shows a possible route for new strategies to overcome resistance to current cancer therapy." (PMID 25885284, 2015). "Bcl-2 was reported to act as an anti-autophagy protein via its inhibitory interaction with Beclin-1 in various cancer cells." (PMID 26311737, 2015). "An increase in Bcl-2 expression protects cancer cells from apoptosis, and the elevated expression of Bcl-2 and Bcl-xL has been frequently observed in a variety of cancers." (PMID 26506422, 2015). "Along similar lines, pharmacological inhibition of intracellular NOX with DPI resulted in a dose dependent decrease in STAT3pTyr705 as well as Bcl-2pSer70 in cancer cells overexpressing Bcl-2." (PMID 26430964, 2015). "Many anti-cancer agents induce the intrinsic apoptotic pathway, which is characterized by increases in the Bax/Bcl2 ratio, the activation of caspases and cleavage of PARP." (PMID 25603347, 2015). "Targeting the antiapoptotic proteins such as those of the Bcl-2 family members (Bcl-2, Bcl-xL, Bcl-w, Mcl-1, and A1) is essential for cancer treatment or preventive drug discovery." (PMID 26117852, 2015). "ABT-199, alone or in combination with other anticancer agents, represents a promising strategy against growth of Bcl-2 dependent cancers." (PMID 26090338, 2015). "A variety of small molecules targeting antiapoptotic Bcl-2 proteins have been developed with the aim to overcome cell death resistance in cancer." (PMID 26585594, 2015). "NRF2 also upregulates the transcription of anti-apoptotic proteins, such as Bcl-2 and Bcl-xL, suppressing apoptosis, and increasing survival and drug resistance in cancer cells." (PMID 26247201, 2015). "As in other cancers, Fx has been shown to suppress the level of Bcl-2 protein and induce apoptosis in human colon cancer cells (Caco-2, HT-29 and DLD-1)." (PMID 26264004, 2015). "Specific down regulation of Bcl-2 by antisense oligos or siRNA sensitizes cancer cells to chemotherapy or radiation therapy." (PMID 26535028, 2015). "We observed that both metformin and aspirin significantly inhibited the activity of STAT3, and STAT3 was previously showed to regulate Mcl-1 and Bcl-2 in various cancer cell lines." (PMID 26056043, 2015). "Taken together, PPARα functions as an E3 ubiquitin ligase to induce Bcl2 ubiquitination and degradation, leading to increased cancer cell sensitivity in response to chemotherapy drugs." (PMID 26556865, 2015). "The apoptotic process is determined by the balance of proapoptotic and antiapoptotic proteins and Bcl-2 represents a broad antiapoptotic factor and opposes cell deaths following ionizing radiation, cancer drugs, and hormonal manipulations." (PMID 26075224, 2015). "The overexpression of Bcl-2 contributes to cancer progression, inhibits apoptosis and confers resistance to standard anticancer therapies, limiting treatment options for AML." (PMID 26136223, 2015). "Protamine nanoparticles were designed by encapsulating small hairpin RNA (shRNA)-expressing plasmid DNA targeting the Bcl-2 gene (shBcl-2) to silence apoptosis-related Bcl-2 protein for improving the transfection efficiency and cytotoxicity in cancer therapy." (PMID 25852425, 2015).